RNU6-489P (RNA, U6 small nuclear 489, pseudogene)
Gene: Small nuclear RNA gene on chromosome 17 (37,907,957 to 37,908,063, forward strand). Ensembl gene ENSG00000277341.
Homologues: Orthologues: macaque U6 (95% identical), macaque U6 (93% identical), macaque U6 (92% identical), rat U6 (88% identical), pig U6 (78% identical), dog U6 (76% identical), guinea pig U6 (66% identical). Paralogues in human: RNU6-1192P (100% identical), RNU6-306P (93% identical), RNU6-38P (87% identical), RNU6-658P (86% identical), RNU6-1011P (85% identical), RNU6-29P (85% identical), RNU6-48P (85% identical), RNU6-25P (84% identical), RNU6-28P (84% identical), RNU6-33P (84% identical), RNU6-476P (84% identical), RNU6-664P (84% identical), and 1288 more.